AUP1 (AUP1 lipid droplet regulating VLDL assembly factor)
Description:
Plays a role in the translocation of terminally misfolded proteins from the endoplasmic reticulum lumen to the cytoplasm and their degradation by the proteasome. Plays a role in lipid droplet formation. Induces lipid droplet clustering. Recruits ubiquitin-conjugating enzyme UBE2G2 to lipid droplets which facilitates its interaction with ubiquitin ligases AMFR/gp78 and RNF139/TRC8, leading to sterol-induced ubiquitination of HMGCR and its subsequent proteasomal degradation. Also required for the degradation of INSIG1, SREBF1 and SREBF2. Plays a role in regulating assembly and secretion of very low density lipoprotein particles and stability of apolipoprotein APOB. (Microbial infection) Following Dengue virus infection, required for induction of lipophagy which facilitates production of virus progeny particles.
Tractability: Antibody: UniProt places it where antibodies can reach, with high confidence. PROTAC: UniProt records ubiquitination sites on it; ubiquitination databases record sites on it; its protein half-life has been measured.
Gene: Protein-coding gene on chromosome 2 (74,526,636 to 74,529,788, reverse strand). Ensembl gene ENSG00000115307.
Subcellular location: Endoplasmic reticulum membrane; Lipid droplet; Cytoplasmic vesicle, autophagosome
Subcellular location (Human Protein Atlas): Nucleoplasm; Vesicles
Pathways (Reactome):
Disease: Dengue Virus-Host Interactions
Gene Ontology:
Molecular function: protein binding; ubiquitin conjugating enzyme binding; ubiquitin protein ligase binding; ubiquitin binding
Biological process: ERAD pathway; lipid droplet formation; lipid droplet organization; lipophagy; protein localization to lipid droplet; response to virus; retrograde protein transport, ER to cytosol
Cellular component: autophagosome; endoplasmic reticulum; endoplasmic reticulum membrane; extracellular exosome; lipid droplet; membrane
Genetic constraint (gnomAD): Loss-of-function variants: 30 observed, 53.68 expected, observed/expected ratio (o/e) 0.56, 90% interval 0.42 to 0.76. The upper end of that interval is the gene's LOEUF score, 0.76, which puts it in group 3 of 6, group 1 being the genes least tolerant of losing a copy. Missense variants: 492 observed, 535.18 expected, observed/expected ratio (o/e) 0.92, 90% interval 0.85 to 0.99. Synonymous variants: 227 observed, 214.68 expected, observed/expected ratio (o/e) 1.06, 90% interval 0.95 to 1.18.
Homologues: Orthologues: chimpanzee AUP1 (99% identical), macaque AUP1 (99% identical), dog AUP1 (95% identical), pig AUP1 (94% identical), guinea pig AUP1 (93% identical), rabbit AUP1 (93% identical), mouse Aup1 (90% identical), rat Aup1 (82% identical), zebrafish aup1 (54% identical), tropical clawed frog aup1 (49% identical), Caenorhabditis elegans F44B9.5 (31% identical).
Diseases named in the same sentence as AUP1 in open-access papers:
AUP1 is named in the same sentence as 22 diseases in open-access papers, as found by Europe PMC text mining. Sharing a sentence is not in itself a finding about the gene and the disease. The quoted sentences say what the papers report.
glioblastoma (2 papers, 2023 to 2025). The most malignant astrocytic tumor (WHO grade IV). "Hence, the AUP1 could reflect the fibroblast formation and inflamed status, which tends to occur in higher-grade tumors, such as grade 4 glioblastoma." (PMID 37029364, 2023).
glioma (2 papers, 2023 to 2025). A benign or malignant brain and spinal cord tumor that arises from glial cells (astrocytes, oligodendrocytes, ependymal cells). "The current project is the first study to characterize the association between the role of AUP1 in glioma." (PMID 37029364, 2023). "Kaplan–Meier survival analysis demonstrated a poorer prognosis with high AUP1 in pan-glioma, IDH-wildtype, and IDH-mutant astrocytoma but not in oligodendroglioma." (PMID 37029364, 2023). "Next, we investigate the dynamic changes in AUP1 between primary and recurrent tumors using the Glioma Longitudinal AnalySiS (GLASS) dataset." (PMID 37029364, 2023). "In this study, we aimed to characterize the AUP1 in glioma and see if it plays a role similar in renal tumors." (PMID 37029364, 2023). "Here, we aim to use sophisticated bioinformatics and experimental validation to characterize the AUP1's role in glioma." (PMID 37029364, 2023). "The bioinformatics analysis of the TCGA dataset revealed that AUP1 significantly increased in tumor components than normal across all subgroups, including pan-glioma, IDH-wildtype, IDH-mutant astrocytoma, and Oligodendroglioma." (PMID 37029364, 2023). "To further understand the longitudinal changes of AUP1 in glioma patients, we analyzed the primary and recurrent tumors from the Glioma Longitudinal AnalySiS (GLASS) dataset." (PMID 37029364, 2023). "Hence, we set numerous sophisticated bioinformatics analyses from the large-scale database and performed the functional modeling using small interfering RNA targeting the AUP1 gene (siAUP1) to explore its role in glioma." (PMID 37029364, 2023). "In this project, we wonder if AUP1 also plays a similar role in glioma." (PMID 37029364, 2023). "We integrated the single-cell sequencing and CIBERSORT analyses at the Chinese Glioma Genome Atlas (CGGA) and Glioma Longitudinal AnalySiS (GLASS) dataset to rationale the role of AUP1 in glioma." (PMID 37029364, 2023). "In the endothelium, the AUP1 positively correlated to the IDH mutant glioma but negatively to the IDH wildtype astrocytoma." (PMID 37029364, 2023).
viral infection (2 papers, 2019 to 2025). "To gain insight into the importance of AUP1 in host defense against viral infection in vivo, we set out to suppress Aup1 expression in mice with shRNAs delivered by adeno-associated virus serotype 9 (AAV9), which has a high transduction efficiency to many tissues." (PMID 40237449, 2025). "Consequently, we observed strong resistance to viral infections in AUP1 knockout cells." (PMID 40237449, 2025). "However, the mechanism by which DENV stimulates lipophagy was not clear until the elucidation of a critical role for host AUP1 (ancient ubiquitous protein 1) in DENV-promoted lipophage and viral infection." (PMID 30863375, 2019).
astrocytoma (1 paper, 2023). "Secondly, besides the gene mutation, the extrachromosomal DNA (such as EGFR amplification) and chromosome structure (such as chromosome 7 gain with 10 loss) are associated with higher AUP1 in IDH wildtype astrocytoma." (PMID 37029364, 2023). "In the IDH mutant astrocytoma, AUP1 revealed a significant association not only with M0 macrophage but also with M2 macrophage." (PMID 37029364, 2023). "The results of the IDH mutant astrocytoma group showed a similar trend that the AUP1 also correlated with myeloid and T cells." (PMID 37029364, 2023). "From the results, the AUP1 was significantly associated with increased M0 macrophage and depletion of monocytes in IDH wildtype astrocytoma." (PMID 37029364, 2023). "On the contrary, the AUP1 expression was reversely associated with MSI in astrocytoma groups but not Oligodendroglioma." (PMID 37029364, 2023). "In the longitudinal data, the AUP1 significantly dropped in the recurrent IDH wildtype astrocytoma, which might result from increased AUP1-cold components, including oligodendrocytes, endothelial cells, and pericytes." (PMID 37029364, 2023). "Similarly, in the context of the IDH mutant astrocytoma, the tumor with higher AUP1 was significantly correlated with PI3K-AKT-MTOR pathway (EGFR, PDGFRA, TSC2, MTOR), and autophagy signaling (ATG4B)." (PMID 37029364, 2023). "In the IDH wildtype astrocytoma, it was found that AUP1 significantly correlated with higher myeloid and T cells but reversed to B cells, regardless of whether the cancer was primary or recurrent." (PMID 37029364, 2023). "In addition, we noticed that the inflammatory cells, including myeloid and T cells, surprisingly contributed to the AUP1 expression in both IDH wildtype and IDH mutant astrocytoma." (PMID 37029364, 2023). "In the COX-survival analysis, increased AUP1 significantly correlated with a higher hazard ratio in the IDH-wildtype and IDH-mutant astrocytoma but not in the Oligodendroglioma." (PMID 37029364, 2023).
Cirrhosis (1 paper, 2024). A chronic disorder of the liver in which liver tissue becomes scarred and is partially replaced by regenerative nodules and fibrotic tissue resulting in loss of liver function. "The upregulation of AUP1 and downregulation of IGFBP3 expression in liver cells are associated with the development of liver fibrosis and cirrhosis." (PMID 39083563, 2024).
colon cancer (1 paper, 2017). "The AS of CALD1, COL6A3, FN1, MAST2, LGR5 and ITGB4 were previously validated in colon cancer using RT-PCR24, while CLSTN1, AUP1, CTNND1, CALD1 and COL6A3 were shown to exhibit tumour-specific splice variants in colon, bladder and prostate cancers." (PMID 28592875, 2017).
COVID-19 (1 paper, 2024). A disease caused by infection with severe acute respiratory syndrome coronavirus 2. "Seven lipophagy-related genes, including ACADVL, HYOU1, DAP, AUP1, PRXAB2, LSS, and PLIN2, were used as biomarkers and drug targets for COVID-19." (PMID 38932215, 2024). "In sum, this study identifies seven lipophagy-related genes (ACADVL, HYOU1, DAP, AUP1, PRXAB2, LSS, and PLIN2) as biomarkers and potential therapeutic targets for COVID-19." (PMID 38932215, 2024). "The lipophagy-related genes ACADVL, HYOU1, DAP, AUP1, PRXAB2, LSS, and PLIN2 can be used as biomarkers and drug targets for COVID-19." (PMID 38932215, 2024). "In the validation set (GSE190496), we observed a significant increase in the gene expression levels of LSS, HYOU1, ACADVL, PRKAB2, PLIN2, AUP1, and DAP in the COVID-19 group compared to the control group." (PMID 38932215, 2024).
dengue virus infection (1 paper, 2025). "A previous report indicated that dengue virus infection leads to altered AUP1 protein abundance." (PMID 40237449, 2025).
fibrosarcoma (1 paper, 2021). A malignant mesenchymal fibroblastic neoplasm affecting the soft tissue and bone. "To assess the requirement of AUP1 in HRD1-dependent ERAD, we examined the degradation of a known ERAD-L HRD1 substrate, the NHK variant of α1ΑΤ, in HT1080 fibrosarcoma cells." (PMID 34879065, 2021).
neuroblastoma (1 paper, 2021). Neuroblastoma (NB) is the most common solid, extracranial childhood tumor. "A similar loss of UBE2G2 and rescue by GFP-G2BR overexpression was observed in HEK293 AUP1 KO cells, and a dependency of E2 stability on AUP1 was also observed in M17, a neuroblastoma cell line." (PMID 34879065, 2021).
oligodendroglioma (1 paper, 2023). A well-differentiated (WHO grade II), diffusely infiltrating neuroglial tumor, typically located in the cerebral hemispheres. "For Oligodendroglioma, AUP1 is significantly associated with M1 macrophage." (PMID 37029364, 2023). "TCGA data analyses showed that AUP1 expression was significantly associated with increased M0 macrophage in IDH wildtype, M0 and M2 macrophage in IDH mutant, and M1 macrophage in oligodendroglioma." (PMID 37029364, 2023).
ovarian carcinoma (1 paper, 2025). A malignant neoplasm originating from the surface ovarian epithelium. "Our study revealed that overexpression of the SUMOylation-related gene AUP1 is associated with the resistance of ovarian cancer cells to paclitaxel and carboplatin chemotherapy regimens." (PMID 40534859, 2025). "Furthermore, patients with high AUP1 expression were older and presented with more advanced disease stages, highlighting the close association between AUP1 and clinical risk factors in ovarian cancer patients." (PMID 40534859, 2025). "Through integrated machine learning and single-cell analysis, we identified five prognostic-associated SRGs (PI3, AUP1, CD200, GNAS and CCDC80) regulated by global SUMOylation levels in ovarian cancer." (PMID 40534859, 2025). "Through single-cell analysis, we further identified five potential prognostic biomarkers associated with the ovarian cancer cell functional pathway and TIME: three risk genes PI3, AUP1 and CCDC80 and two protective genes CD200 and GNAS." (PMID 40534859, 2025). "On the whole, our study identified five key SRGs, including the risk genes AUP1, PI3 and CCDC80, as well as the protective genes CD200 and GNAS and elucidated their prognostic potential in ovarian cancer." (PMID 40534859, 2025). "Therefore, AUP1 expression levels in cancer cells could serve as biomarkers for predicting ovarian cancer sensitivity to postoperative chemotherapy with paclitaxel and carboplatin." (PMID 40534859, 2025).
renal clear cell carcinoma (1 paper, 2023). "Most recently, it was addressed that AUP1 influences lipid metabolism and accelerates the development of renal clear cell carcinoma by inducing lipid accumulation." (PMID 37029364, 2023). "In cancer research, the AUP1 has even been discovered to influence lipid metabolism and accelerate the development of renal clear cell carcinoma by inducing lipid accumulation recently." (PMID 37029364, 2023).
tumor (6 papers, 2017 to 2025). "Through bioinformatics analyzing the TCGA genomic and proteomic datasets, we noticed the AUP1 did increase in the tumor component, relevance to the tumor grading, and associated with overall survival." (PMID 37029364, 2023). "Instead, we noticed AUP1 expression associated with tumor proliferation, the number of myeloid cells, dendritic cells, T cells, B cells, granulocytes, and some stromal cells." (PMID 37029364, 2023). "At the same time, EGFR amplification and Chromosome 7 gain combined 10 loss are associated with increased tumor growth related to AUP1 levels." (PMID 37029364, 2023). "Instead, we noticed AUP1 expression associated with tumor proliferation and inflammatory status, contributed by myeloid cells and T cells." (PMID 37029364, 2023). "Through this study, we learned that AUP1 is a poorer predictive biomarker associated with tumor proliferation and could report inflamed microenvironments in the tissue, potentially a clinical application." (PMID 37029364, 2023). "So far, we have understood the amount of AUP1 linked to the myeloid cells and partly tumor cells." (PMID 37029364, 2023). "This study taught us that AUP1 is a poorer predictive biomarker associated with tumor proliferation and could report inflamed status, potentially impacting the clinical application." (PMID 37029364, 2023). "AUP1 regulates LD turnover and protein quality control, suggesting a role in tumor metabolic adaptation and potential therapeutic targeting." (PMID 40370434, 2025). "We observed that mice injected with AUP1 OE ID8 cells exhibited a significantly higher tumor burden than the NC OE group." (PMID 40534859, 2025). "In the tumor components, we found that AUP1 correlates positively with proliferative stem cells in all three subtypes among different databases, which is compatible with previous experimental validation." (PMID 37029364, 2023). "The results showed that the tumor cells revealed higher AUP1 expression than the normal brain lysates, similar to the previous bioinformatics analyses." (PMID 37029364, 2023). "From the single-cell sequencing and CIBERSORT analyses at CGGA and GLASS data, we understood the AUP1 expression was affected by the tumor proliferation, stromal, and inflammation compositions, particularly the myeloid and T cells." (PMID 37029364, 2023). "The heatmap of the single-cell sequencing analyses showed that the tumor cells revealed variable expression, and only part of them showed high AUP1 expression." (PMID 37029364, 2023). "Firstly, the AUP1 is a prognostic marker, increased in the tumor component, and correlated with tumor grade in both transcriptomes and protein levels." (PMID 37029364, 2023). "The earlier bioinformatics characterization and functional validation showed that AUP1 correlated with tumor grade and proliferation function." (PMID 37029364, 2023). "Firstly, we confirmed that AUP1 expression at several tumor cell lines, including the U87MG, U118MG, LN229, LNZ308, and GBM8401." (PMID 37029364, 2023). "As the transcriptomes showed, the AUP1 protein expression was significantly higher in the tumor components than in the normal component." (PMID 37029364, 2023). "Comparing AUP1 knockdown to controls, tumor growth, size, and weight were all reduced." (PMID 37033251, 2023). "During tumor recurrence, AUP1 levels increased with fibroblasts but inverted to oligodendrocytes." (PMID 37029364, 2023).
tumor (continued). "Although the NC OE group showed a marked reduction in tumor burden following TC treatment, the same regimen did not significantly reduce the tumor burden in AUP1 OE mice." (PMID 40534859, 2025). "From the results, we noticed that tumor cells highly expressed AUP1 significantly correlated with proliferation marker (MCM2, MCM6), PI3K-AKT-MTOR pathway (Akt1, TSC1, mTOR, Foxo1), and autophagy signaling (Atg3, Atg4B, Atg4D, Atg7, Atg9A, Atg16L1) in IDH wildtype tumor cells." (PMID 37029364, 2023).
infection (4 papers, 2021 to 2025). The state of being infected such as from the introduction of a foreign agent such as serum, vaccine, antigenic substance or organism. "In contrast, Aup1−/− cells displayed impaired LD turnover, maintaining elevated LD numbers throughout the infection time course." (PMID 41306517, 2025). "As anticipated, Ube2g2 interacted with Aup1 in both mock and virus-infected samples during the course of infection." (PMID 37164963, 2023). "Next, to explore whether AUP1 influences the innate immune response induced by RNA viruses, we examined the phosphorylation levels of relevant proteins following infection with vesicular stomatitis virus (VSV) at different time points." (PMID 40237449, 2025). "In addition, enzyme-linked immunosorbent assay (ELISA) results indicated that the protein levels of IFN‐β in the serum were much higher in mice injected with AAV-sh-Aup1 than in wild‐type mice 24 h after intravenous infection with HSV‐1." (PMID 40237449, 2025). "Defective lipophagy was not due to loss of Aup1, since its expression levels in Ube2g2-deficient cells remained unaffected even at late timepoints in infections." (PMID 37164963, 2023). "Notably, infection with the RNA virus vesicular stomatitis virus (VSV) promotes the accumulation of lipid droplets (LDs) and AUP1 proteins." (PMID 40237449, 2025). "Additionally, infection with VSV led to an accumulation of AUP1 protein levels in various cell types, while no significant accumulation was observed during VACV and HSV-1 infections." (PMID 40237449, 2025).
cancer (2 papers, 2023 to 2025). A tumor composed of atypical neoplastic, often pleomorphic cells that invade other tissues. "In cancer cells, the expression of four SRGs (PI3, AUP1, CD200 and GNAS) is closely associated with epigenetic regulation and epithelial-mesenchymal signaling." (PMID 40534859, 2025).
AUP1 also shares sentences with these, for which no sentence is quoted: Andermann syndromes (1 paper); Fever (1); hepatoma (1); insulinoma (1); liver fibrosis (1); Obesity (1).